U2 (U2 spliceosomal RNA )
Synonyms: LOC124904135
Gene: Small nuclear RNA gene on chromosome 17 (43,239,921 to 43,240,111, reverse strand). Ensembl gene ENSG00000275616.
Gene Ontology:
Molecular function: pre-mRNA branch point binding
Biological process: mRNA branch site recognition
Cellular component: U2 snRNP
Homologues: Orthologues: chimpanzee U2 (100% identical), macaque U2 (100% identical), dog U2 (99% identical), pig U2 (48% identical), rat LOC120094029 (36% identical). Paralogues in human: U2 (100% identical), RNU2-2 (96% identical), U2 (95% identical), RNU2-3P (93% identical), RNU2-4P (93% identical), RNU2-17P (90% identical), RNU2-6P (90% identical), RNU2-48P (89% identical), RNU2-52P (89% identical), RNU2-59P (89% identical), RNU2-25P (87% identical), RNU2-26P (87% identical), and 68 more.